Y_RNA (Y RNA )
Gene: Miscellaneous RNA gene on chromosome 4 (40,826,655 to 40,826,765, reverse strand). Ensembl gene ENSG00000207195.
Homologues: Orthologues: chimpanzee Y_RNA (100% identical), macaque Y_RNA (96% identical). Paralogues in human: RNY1 (86% identical), Y_RNA (86% identical), Y_RNA (85% identical), Y_RNA (84% identical), RNY1P8 (83% identical), Y_RNA (83% identical), Y_RNA (82% identical), RNY1P11 (81% identical), Y_RNA (81% identical), Y_RNA (80% identical), RNY1P10 (79% identical), RNY1P13 (79% identical), and 96 more.